ENSG00000283782 (novel protein)
Gene: Protein-coding gene on chromosome 5 (132,410,832 to 132,646,079, forward strand). Ensembl gene ENSG00000283782.
Genetic constraint (gnomAD): Loss-of-function variants: 118 observed, 159.48 expected, observed/expected ratio (o/e) 0.74, 90% interval 0.64 to 0.86. Missense variants: 1,225 observed, 1,464.9 expected, observed/expected ratio (o/e) 0.84, 90% interval 0.8 to 0.88. Synonymous variants: 481 observed, 480.42 expected, observed/expected ratio (o/e) 1, 90% interval 0.93 to 1.08.